ERCC1 (ERCC excision repair 1, endonuclease non-catalytic subunit)
Diseases named in the same sentence as ERCC1 in open-access papers (continued):
Sharing a sentence is not in itself a finding about the gene and the disease.
tumor (continued). "Above all, to achieve a better chemotherapy effect and prevent tumour recurrence, the TOP2A, RRM1, HER2 and ERCC1 mRNA or protein expression levels in NMIBC tissues could be detected after NMIBC." (PMID 35711974, 2022). "In addition, a better response to gemcitabine was observed in the tumours with a low expression of both RRM1 and ERCC1." (PMID 35711974, 2022). "We then investigated if a distinct genotype combination of ERCC1, ERCC2 and ERCC5 genes could influence the expression levels of these genes in the tumor tissue." (PMID 35955506, 2022). "It means ERCC1 expression of liver metastases can not be assessed in archived material (primary tumor biopsies), implying the need to use tissue from actual tumor burden to evaluate ERCC1 expression." (PMID 36348319, 2022). "The results suggested that the ERCC1 level, and the level of radiation that the cells were exposed to, were not key in terms of affecting tumor generation." (PMID 36230725, 2022). "Our results suggest that a greater ERCC1 expression in mt KRAS tumors might increase platinum resistance in this group of patients, whereas the greater expression of BRCA1 in wt KRAS tumor might be suggestive of the sensitivity of taxanes." (PMID 35877239, 2022). "After adjustment for tumor grade and molecular subtype, a linearregression model with rank transformation showed that the DNA expression of 2genes (PALB2 and ERCC1) assessed in pre-NACTbiopsies was lower in the pCR group than in the non-pCR group (P=0.014 andP=0.040, respectively)." (PMID 35293552, 2022). "Although immunohistochemistry analyses were performed on a small cohort, these findings suggest that the absence of ERCC1 tumor expression holds a prognostic and potentially predictive value as biomarker in response to adjuvant SOX." (PMID 33671266, 2021). "Exploratory biomarker analyses demonstrated potential benefit for patients with Excision repair cross-complementation group 1 (ERCC1) negative tumor expression." (PMID 33671266, 2021). "Patients with ERCC1 negative tumor expression had significantly better survival compared to ERCC1 positivity (p = 0.01)." (PMID 33671266, 2021). "This phenomenon may constitute an underexplored mechanism of chemoresistance in tumor cells under EMT, implying that expression of the genes DPYD, TYMS, MTHFR, ERCC1, ERCC2, XRCC1, and GSTP1 may be modulated EMT-TFs." (PMID 33429840, 2021). "Reasons for ineligibility were insufficient tumor tissue for the analysis of the ERCC-1 gene SNPs (N = 25 patients) and lack of measurable lesions per RECIST v.1.1 at baseline (N = 6 patients)." (PMID 32983959, 2020). "Notably, in vitro cell culture data showed that XPA, ERCC1 and XPF levels are generally lower in GCT cell lines than in cell lines from other tumour types." (PMID 31906898, 2020). "We analyzed tumor samples from 24 patients and using IHC studied expression of select molecular markers known to be involved in the pathogenesis of HPV+ HNSCC including ERCC1, 4EBP1, AMPK, AKT, S6, PI3K, mTOR, and PTEN." (PMID 32944296, 2020). "The evaluation of overall survival among patients with ERCC1-negative tumor, 1, 3, 5 and 10-year overall survival rate were 100%, 96%, 89% and 62%, compared to 100%, 85%, 57% and 9% for patients with positive expression of ERCC1 (p=0.001) (Figure-3A)." (PMID 32167697, 2020). "Hypothesizing a causal relationship between low sPD-L2 levels and the presence of ERCC1+CTC, one might argue that sPD-L2 mediated anti-tumor activity might play an important role in the prevention of tumor spread to the bone marrow and the elimination of CTCs." (PMID 31681568, 2019). "In conclusion, our results indicate that the ERCC1 rs3212986 and the ERCC2/XPD rs1799793 could be used as surrogate markers for a better stratification of EC patients with advanced resectable tumor." (PMID 30847299, 2019). "Parameter β2 quantifies how ERCC1 expression affects tumor growth when there is no drug intervention, as seen from the vehicle growth curves." (PMID 31331301, 2019).
tumor (continued). "Our results agree with the observations that MCM2, MLH1 and ERCC1 may serve as an oncogene and that PARP1 may function as tumor suppressors genes during tumorigenesis." (PMID 31598158, 2019). "The increased sensitivity to SG3199 of cells defective in homologous recombination repair and DNA repair protein ERCC1 for SG200023, suggest a possible widening of therapeutic index in patients with tumours harbouring these defects, and indicates potential biomarkers of response." (PMID 29992976, 2018). "Moreover, the involvement of ERCC1-XPF in the removal of damages induced during platinum-chemotherapy and radiotherapy of various cancer types, results in tumor resistance to these treatments." (PMID 30563071, 2018). "Given the roles of PARP1, ERCC1, and XPF in the repair of DNA damage, one might expect that increased expression would enhance tumor survival." (PMID 29681762, 2018). "Low levels of ERCC1 expression were hypothesized to reflect decreased NER capacity and thus explain the increased tumor sensitivity to cisplatin-mediated DNA damage and improved clinical outcomes among cisplatin-treated bladder cancer patients." (PMID 28346378, 2017). "Analyzing subsets of tumors with comparable traditional and quantitative Gleason grades revealed that ERCC1 expression measurement did not provide very much additional prognostic impact in morphologically characterized tumor sets." (PMID 28747165, 2017). "Most interestingly, the presence of ERCC1pos CTCs at primary diagnosis was an independent predictor for platinum-resistance whereas ERCC1-expression in the corresponding primary tumor tissue predicted neither platinum-resistance, nor prognosis." (PMID 27049920, 2016). "Previous clinical trials, however, have found limited, if not negative, predictive effects of ERCC1 expression (as measured by IHC in tumor tissue) on the efficacy of platinum-containing chemotherapy." (PMID 27813497, 2016). "Investigating the same six xenografts’ response to each of three therapies: cisplatin, cetuximab, and radiation, provided a controlled environment in which to relate tumor responses to the pre- and posttreatment expression of five potential predictive biomarkers: EGFR, pEGFR, pAkt, pERK, and ERCC1." (PMID 25619980, 2015). "ERCC1 and ERCC2 (XPD) have pivotal roles in the NER pathway, this has been evidenced in studies where lower levels of intratumoral ERCC1 mRNA are significantly correlated with improved survival due to enhanced tumor cell sensitivity to cisplatin." (PMID 25452763, 2014). "However, as demonstrated from the multitude of clinical studies, quantitative analysis of RRM1, ERCC1, and BRCA1 mRNA expression levels has been performed mainly on tumor specimens obtained from fiberoptic bronchoscopy biopsy or surgical resection." (PMID 24591771, 2014). "Tumor RRM1, ERCC1, and BRCA1 mRNA expression levels were analyzed by quantitative RT-PCR." (PMID 24591771, 2014). "Otherwise, we found no statistical relationship between ERCC1 nuclear protein expression or platinum/radiotherapy adjuvant treatment and patient survival following surgical tumor resection in ESCC." (PMID 25191856, 2014). "Log-rank analysis revealed no significant connection between tumor ERCC1 expression (P = 0.12) or adjuvant therapy (P = 0.56) on patient survival." (PMID 25191856, 2014). "As neither tumor ERCC1 expression nor adjuvant treatment was significantly related with patient outcome, it seems unlikely these two variables interacted." (PMID 25191856, 2014). "This study supported our findings that ERCC1-tumor expression had no bearing for predicting patient survival or tumor recurrence regardless of adjuvant chemotherapy." (PMID 25191856, 2014).
tumor (continued). "Hence, for these 7 genes (TS, FPGS, GGH, DHFR, ERCC-1, TOPO-1, and EGFR), evaluation of their expression by biopsy would reflect the mRNA expression in the whole tumor and would therefore permit their use in the clinic." (PMID 23577026, 2013). "Although low expression of ERCC1 is related to carcinogenesis, high expression could enhance the NER, leading to rapid repair of the damaged tumor DNA after chemotherapy, a plausible mechanism of multi-drug resistance in many cancers." (PMID 23046742, 2012). "ERCC1 and BAG-1 are determinants of survival after surgical treatment of NSCLC, and its mRNA expression in tumor tissues could be used to predict the prognosis of NSCLC treated by platinum." (PMID 22439756, 2012). "The tumor expressed high level of TOPO2A, TOPO1, MRP1, MGMT, BCRP, ERCC1, RRM1, and TS." (PMID 21776193, 2011). "Regardless, a high expression of ERCC1 was strongly correlated with poor survival regardless of tumour location." (PMID 18594541, 2008). "In the future, it seems probable that patients with ERCC1 positive tumours will be treated with non-platinum based regimens, whereas patients with ERCC1 negative tumours will be considered as optimal candidates for platinum-based therapy." (PMID 19578506, 2008). "Additionally, ERCC1 is inconsistently expressed with advancing tumor grade (grade 3 > grade 2 > grade 4 > grade 1), whereas ACTL6A shows significant overexpression with the grade of tumor progression (grade 4 > grade 3 > grade 2 > grade 1)." (PMID 40510426, 2025). "However, the expression of miR‐15a was negatively correlated with the ERCC1 mRNA expression in tumour tissues carrying CC genotype, but not in AA one." (PMID 36181289, 2022). "Additionally, NSCLC patients with complete resection of ERCC1‐negative tumours benefited more from cisplatin‐based adjuvant chemotherapy than those with ERCC1 positive tumours." (PMID 36181289, 2022). "Therefore, tumours with a low expression of both RRM1 and ERCC1 may have weaker DNA repair capacity and are more sensitive to chemotherapy." (PMID 35711974, 2022). "In primary tumor biopsies, ERCC1 negativity did not correlate to survival (p = 0.656)." (PMID 33671266, 2021). "Additionally, because the ERCC1-XPF dimer excises the platinum adducts, it is rational to examine whether XPF expression levels correlate with tumor cells resistant to platinum drugs." (PMID 31450627, 2019). "In ER− tumours, that received no chemotherapy, ERCC1 did not influence survival." (PMID 31405143, 2019). "Specifically, the expressions of RRM1, ERCC1, and TUBB3 are inversely correlated with tumor responses to anti-metabolites such as gemcitabine, platinum-based agents, and spindle poisons, respectively, which may help explain why these drugs have shown little efficacy in vivo or in clinical studies." (PMID 29487694, 2018). "Thus, the use of ERCC1 (and/or other NER genes) as predictors of tumor prognosis may be an important clinical strategy." (PMID 30208165, 2018). "Finally, we show that the inhibition of ERCC1/XPF by the EGCGprodrug, Pro-EGCG (EGCG octaacetate), could significantly enhance response to cisplatin in tumor xenografts in vivo by increasing tumor cell death and decreasing proliferation." (PMID 30400270, 2018). "Elevated ERCC1 (HR = 2.1, 95% CI: 1.1–3.9), DKK1, CXCL12, long non-coding RNA MALAT-1 (OR = 3.65, 95% CI: 1.86–7.18) in tissue sample, and detection of circulating tumor cells (pooled HR: 2.36, 95% CI 1.41–3.96) in peripheral blood were risky factors for patients survival." (PMID 29340021, 2017). "However when thresholds for classifying patients as positive and negative were used, 33% of tumours ERCC1 negative by RTqPCR were IHC positive and 32% IHC-negative tumors were classed as ERCC1 positive using RTqPCR." (PMID 26775588, 2016).
tumor (continued). "This disagreement could be circumvented by applying a binarized version of the scoring system, where tumor specimens can be assigned to either a positive (scores 2, 3) or negative (scores 0, 1) ERCC1 expression level category." (PMID 24603753, 2014). "Importantly, CDDP treatment induced a significant increase of ERCC1 gene expression in tumor and in normal cells, while MMC and 5-FU did not." (PMID 24817012, 2014). "Finally, the antibody was used in tumor specimens from a stage III CRC cohort, where oxaliplatin remains part of standard treatments, to test its ability to determine varying levels of ERCC1 expression in patient tumors, and therefore also its ability to potentially aid in clinical decision making." (PMID 24603753, 2014). "Several studies have shown that high ERCC1 expression is a good prognostic factor in patients without cisplatin-based chemotherapy and also a predictor for poor clinical outcome in patients with cisplatin-based chemotherapy for various tumor types." (PMID 22616552, 2012). "However, in tumours not exposed to neoadjuvant chemotherapy, ERCC1 expression did not correlate with survival, implying that ERCC1 is likely to have predictive significance rather than prognostic significance in these tumours." (PMID 20461087, 2010). "Among 761 tumours, ERCC1 expression was positive in 335 (44%) and negative in 426 (56%)." (PMID 20461087, 2010). "It is possible that the predictive value of ERCC1 is related to its role in TC-NER and that the expression of other proteins involved in TC-NER, like CSB, may also be predictors of therapeutic response in diverse tumours." (PMID 20470425, 2010). "In 2/10 unmatched tumor tissue samples, allelotyping data could be obtained for ERCC1 but not for ERCC2 and XRCC1, probably due to poor FFPE DNA quality." (PMID 20066159, 2009). "This may be significant since it has not been shown that ERCC1 expression is identical in the primary tumour and its metastatic locations." (PMID 19578506, 2008). "Consequently, the expression of different isoforms could be a major concern as it would lead to a tumor being considered ERCC1-positive, although the expressed protein might be non-functional." (PMID 39735668, 2025). "This is in contrast to the clear but non-significant upregulation in ERCC1 (p = 0.080) and RFC1 (p = 0.075) between the tumours and normal muscle tissue of the COS patients." (PMID 39335211, 2024). "ERCC1 expression had no predictive and prognostic significance with regard to OS, PFS or tumor shrinkage." (PMID 39516666, 2024). "In contrast, significantly lower mRNA expression in tumor samples with high CIN70 score was observed for SMC1 (**), ERCC1 (***) and LIG4 (****), and a non-significant for XRCC4 (n.s.)and BOD1L1 (n.s.)." (PMID 33801877, 2021). "Primary tumours expressing low/no ERCC1 (DLD‐C2) exhibited a significant reduction in fluorescence signal and tumour weight upon oxaliplatin treatment indicating tumour shrinkage." (PMID 33931939, 2021). "Unfortunately, the data regarding the very expression of ERCC1 in patients with TNBC alone is lacking, but although the tumor genome considerably differs from the host genome, it is plausible that it still carries some resemblance." (PMID 29507678, 2018). "Patient #6 was also one of the few who failed to exhibit ERCC1 and EGFR protein modulation after radiation therapy in tumor tissues." (PMID 29160417, 2017). "Most interestingly, we discovered the presence of ERCC1+CTC at primary diagnosis to be an independent predictor for platinum-resistance, whereas ERCC1-expression in corresponding primary tumor tissue predicted neither platinum-resistance nor prognosis." (PMID 28415744, 2017). "The expression of HNF1A-AS1 in tumor samples was also significantly correlated with one immunohistochemical markers of cancer, RRM1 (p = 0.006), but not with VEGF, C-erbB-2, TS, BRCA1, ERCC1, Ki67, CD56, Syn, or CgA." (PMID 26472090, 2015).
tumor (continued). "So, in this study, we use RT-PCR to examine the expression of ERCC1, BAG-1, BRCA1, RRM1 and TUBB3 in tumor samples from patients with resected NSCLC not receiving adjuvant chemotherapy." (PMID 22439756, 2012). "Our results strongly suggest that tumours with high DPD and ERCC1 gene expression are unlikely to respond to current standard therapy, resulting in inadequate tumour control and poor outcomes." (PMID 18231104, 2008). "ERCC1 negativity, a marker of platinum response, was frequently correlated with both MSI‐H and TMB‐H status in the pooled analysis of tumors but was not correlated with PD‐L1 IHC‐positive status across tumor types." (PMID 31479512, 2020). "When tumour tissue samples from the same patients originally enrolled in the IALT trial were re-evaluated using exactly the same IHC procedures, 36% of patients classed as ERCC1 positive on one occasion were classed as negative on another.." (PMID 26775588, 2016). "The results of these investigations suggest that ERCC1 has no predictive value for or against radiochemotherapy in HNSCC on its own, but is an indicator of well-known tumor cell factors as radiosensitive cell cycle phase and normoxic condition, which influence treatment outcome." (PMID 24817012, 2014). "In addition, we presented separate analyses for ORR of primary tumor and neck nodes based on BRCA1 and ERCC1 expression in primary NPC in order to assess whether or not the different treatments affect the primary tumor and the metastatic sites." (PMID 28404895, 2017).